RNU6-399P (RNA, U6 small nuclear 399, pseudogene)
Gene: Small nuclear RNA gene on chromosome 12 (62,545,582 to 62,545,679, reverse strand). Ensembl gene ENSG00000202034.
Homologues: Orthologues: chimpanzee U6 (98% identical), chimpanzee U6 (94% identical), macaque U6 (93% identical), dog U6 (72% identical), guinea pig U6 (72% identical), dog U6 (63% identical), mouse Gm25549 (58% identical). Paralogues in human: RNU6-1124P (86% identical), RNU6-338P (86% identical), RNU6-708P (86% identical), RNU6-790P (86% identical), RNU6-1075P (85% identical), RNU6-1117P (85% identical), RNU6-116P (85% identical), RNU6-140P (85% identical), RNU6-166P (85% identical), RNU6-41P (85% identical), RNU6-1060P (84% identical), RNU6-1145P (84% identical), and 1289 more.